SGK1 (serum/glucocorticoid regulated kinase 1)
Diseases named in the same sentence as SGK1 in open-access papers (continued):
Sharing a sentence is not in itself a finding about the gene and the disease.
epilepsy (3 papers, 2017 to 2024). A brain disorder characterized by episodes of abnormally increased neuronal discharge resulting in transient episodes of sensory or motor neurological dysfunction, or psychic dysfunction. "Therefore, SGK1 very probably is a functional epilepsy associated gene." (PMID 28255556, 2017). "The SGK1 subtype, SGK1.1, appears to play an important role in suppressing epilepsy, particularly in neurons where SGK1.1 can specifically activate and up-regulate M currents to reduce the severity and mortality of persistent seizures." (PMID 39737082, 2024). "However, a large number of studies have shown that inhibiting the expression level of SGK1 is conducive to the treatment of epilepsy and SGK1 will be an important therapeutic target." (PMID 39737082, 2024). "The role of SGK1 in epilepsy has also been studied in recent years." (PMID 39737082, 2024). "However, both SGK1 S78 and S422 phosphorylation ratios were lower in epilepsy rats than those in control animals." (PMID 34440273, 2021). "It has been confirmed that aldosterone has strong chemical and biological effects on epileptic seizures, implying that our predicted gene SGK1 may contribute to the regulation of the typical symptoms of epilepsy, the seizures." (PMID 28255556, 2017). "Therefore, inhibition of NEDD4–2 degradation could be achieved through downregulation of the expression and content of SGK1, which in turn can regulate epilepsy through the SGK1-NEDD4–2 pathway." (PMID 39737082, 2024). "Therefore, the molecular mechanism of SGK1 in epilepsy needs to be further explored." (PMID 39737082, 2024). "The remaining two genes SGK1 and YES1 have also been suggested to contribute to the progression of epilepsy." (PMID 28255556, 2017). "In this paper, we reviewed the role of SGK1 in various neurological diseases such as AD, PD and epilepsy, etc., and found that SGK1 may play a positive feedback, negative feedback, or dual roles according to its "role" in the signaling pathways involved in various diseases." (PMID 39737082, 2024).
experimental autoimmune encephalomyelitis (3 papers, 2015 to 2019). An autoimmune demyelinating disease of the central nervous system that is produced experimentally in animals by the injection of homogenized brain or spinal cord in Freund's adjuvant. "Here, we used an experimental autoimmune encephalomyelitis (EAE) model for MS to study the role of p38MAPK/SGK1 signaling in the macrophage polarization and its effects on the development and severity of EAE." (PMID 30716717, 2019).
Huntington disease (3 papers, 2011 to 2024). Huntington disease (HD) is a rare neurodegenerative disorder of the central nervous system characterized by unwanted choreatic movements, behavioral and psychiatric disturbances and dementia. "CBG treatment led to the downregulation of Cd44 and Sgk1, suggesting potential normalization of gene expression related to Huntington’s disease physiopathology." (PMID 38891938, 2024). "A specific Huntington’s disease array analysis identified Cd44 and Sgk1 as significantly upregulated genes in 3NP mice." (PMID 38891938, 2024).
Hydrocephalus (3 papers, 2022 to 2023). Hydrocephalus is an active distension of the ventricular system of the brain resulting from inadequate passage of CSF from its point of production within the cerebral ventricles to its point of absorption into the systemic circulation. "Finallym we suggest the use of Sgk1 inhibitors in the treatment of symptoms (hydrocephalus) associated with cilyopathies in which a dysregulation of the canonical and non-canonical Wnt pathways leads to the stabilization and activation of beta catenin." (PMID 36982349, 2023). "In vivo, MRI studies were performed in a genetic rat model of hydrocephalus to determine effects of inhibition of SGK1 with a novel inhibitor, SI113." (PMID 37596666, 2023). "The data presented in this manuscript provide innovative preclinical proof-of-concept and proof-of-mechanism studies for SGK1 as a therapeutic target in the treatment of hydrocephalus." (PMID 37596666, 2023). "Next, quantitative PCR was used to determine potential changes in the gene expression of Trpv4 and Sgk1 that may be modified by hydrocephalus or SI113 treatment." (PMID 37596666, 2023). "We postulated that despite the lack of significant changes in gene expression, perhaps the abundance and/or phosphorylation of SGK1 and TRPV4, as well as some downstream targets of SGK1, would be changed due to hydrocephalus and/or drug treatment." (PMID 37596666, 2023). "We show compelling evidence that SI113 inhibits SGK1 activity and corresponding TRPV4 activation in the choroid plexus, and that SI113 treatment inhibits the progression of hydrocephalus in a preclinical rodent model." (PMID 37596666, 2023). "The current studies highlight a novel drug target, serum- and glucocorticoid-induced kinase 1 (SGK1) within the TRPV4 pathway and show the efficacy of an inhibitor of SGK1 in the treatment of hydrocephalus in vivo and mechanistically in a human cell line in vitro." (PMID 37596666, 2023). "Mechanistically, the development of hydrocephalus in the rat model involves an increase in activated, phosphorylated SGK1 with no change in the total amount of SGK1." (PMID 37596666, 2023). "Hydrocephalus, commonly found in MKS3, can be the consequence of an imbalance in fluid-electrolyte homeostasis, finely regulated by ion transporters like TRPV4, whose expression is controlled by Sgk1." (PMID 36982349, 2023). "We have shown that SGK1 activity is important for TRPV4 activation during choroid plexus-mediated stimulation of electrolyte and fluid secretion, making this pathway an attractive target in the treatment of homeostatic disorders such as hydrocephalus." (PMID 37596666, 2023). "Additionally, the ratio of p-SGK1 (t256) to SGK1 (a representation of SGK1 activity), also did not change due to hydrocephalus." (PMID 37596666, 2023).
Hyperkalemia (3 papers, 2017 to 2023). An abnormally increased potassium concentration in the blood. "The WNK4 phosphorylation by cSrc or SGK1, activated by angiotensin II or aldosterone, respectively, is another relevant mechanism of NCC, ENaC, and ROMK modulation in states such as volume reduction, hyperkalemia, and hypokalemia." (PMID 36790288, 2023).
hyperphosphatemia (3 papers, 2019 to 2020). Abnormally high level of phosphate in the blood. "Inhibition or deficiency of SGK1 is able to suppress vascular calcification during hyperphosphatemia." (PMID 30887097, 2019). "In addition, SGK1 mediates the induction of osteo-/chondrogenic transdifferentiation and, thus, vascular calcification by other pathological factors such as hyperphosphatemia or mineralocorticoid excess." (PMID 30706178, 2019). "Thus, interference with SGK1/NF-kB signaling pathway may preserve an anti-calcific environment of VSMCs and ameliorate vascular calcification during hyperphosphatemia." (PMID 30887097, 2019).
injury (3 papers, 2011 to 2023). Damage inflicted on the body as the direct or indirect result of an external force, with or without disruption of structural continuity. "Previous work reported a connection between E2 activities and SGK1 phosphorylation in LPS-induced acute lung injury." (PMID 37226177, 2023). "Our previous studies have demonstrated that SGK1 is of great importance in the regulation of ENaC-mediated AFC during acute lung injury." (PMID 31160894, 2019). "Since brain injury does not induce the elevation of plasma corticosterone levels, a mechanism other than the activation of the HPA pathway is involved in the upregulation of Sgk1 after brain injury." (PMID 21655274, 2011).
ischemic stroke (3 papers, 2017 to 2024). A stroke disorder caused by obstruction of blood flow to the brain, due to thrombotic (local blood clot formation) or embolic (due to a blood clot or other material traveling from another site) event. "Therefore, it can be hypothesized that activating the expression of SGK1, which is partially associated with microglia, contributes to the treatment of ischemic stroke." (PMID 39737082, 2024). "Intracarotid cold saline infusion increases the expression of SGK1 and decreases the expression of autophagy markers beclin-1 and LC-3 in a rat model of ischemic stroke, thereby creating a neuroprotective effect on stroke." (PMID 39737082, 2024).
leukemia (3 papers, 2017 to 2025). A malignant (clonal) hematologic disorder, involving hematopoietic stem cells and characterized by the presence of primitive or atypical myeloid or lymphoid cells in the bone marrow and the blood. "There are few reports of SGK1 acting in leukemia, most of them describing an SGK1 loss of function, as could be expected of a tumor suppressor." (PMID 40613901, 2025). "Future studies are warranted to assess if the therapeutic targeting of the WT1/SGK1 pair could help induce leukemia cell maturation or apoptosis." (PMID 40613901, 2025). "Thus, the reduction of WT1 and induction of SGK1 levels appear to be a common phenomenon during differentiation in the hematopoietic and leukemia models." (PMID 40613901, 2025). "So, the repressive effect of WT1 on SGK1 expression was specific for WT1 isoforms, at least in these non-leukemia cell lines." (PMID 40613901, 2025). "Some other downregulated genes are related to chemo-resistant or leukemia aggressiveness such as Thbs1, Tgm2, Ambp, and the AF9 regulator Sgk1, which negatively regulates the DOT1A-AF9 repressor complex." (PMID 28974232, 2017).
liver cancer (3 papers, 2015 to 2023). An epithelial or non-epithelial malignant neoplasm that arises from the liver. "Recent findings also have shown that SGK-1 regulates cell survival, proliferation, and differentiation in several types of cancer cells such as kidney, breast, and liver cancer." (PMID 33083492, 2020). "Although no experimental data pertaining to AGAP11 have been reported in the field of cancer, there is evidence to suggest that closely related genes, namely, LPL, MMP9, SGK1, TLR4, and FOS play certain roles in liver cancer through different mechanisms." (PMID 36726348, 2023).
liver cirrhosis (3 papers, 2015 to 2023). "In HCC, SGK1 expression is particularly relevant in highly malignant tumors characterized by epithelial-to-mesenchimal transition (EMT) that supports the underlying liver cirrhosis." (PMID 26462020, 2015).
meningioma (3 papers, 2015 to 2017). A generally slow growing tumor attached to the dura mater. "In NF2-deficient meningioma cells, inhibition of SGK1 rescues mTORC1 activation, and SGK1 activation is sensitive to dual mTORC1/2 inhibitor AZD2014, but not to rapamycin." (PMID 26219339, 2015). "GBM samples (n=13) showed a 3.9 fold increase in SGK1 mRNA expression compared to control samples (n=5) (P=0.01), whereas meningioma samples (n=2) were characterized by a level of SGK1 mRNA expression comparable with the one of normal brain tissue." (PMID 26908461, 2016). "Here we establish that, in addition to mTORC1 activation, mTORC2-dependent activation of SGK1/NDRG1 is commonly seen in human meningioma cells, which remains unaffected by rapamycin treatment." (PMID 26219339, 2015). "We further show elevated expression of SGK1 accompanied by constitutive activation of SGK1 as detected by phosphorylation of its specific target NDRG1, in human arachnoidal and meningioma cells with NF2 loss." (PMID 26219339, 2015). "Our results convincingly show that activation of the mTORC2-target SGK1/NDRG1 in human meningioma cells is sensitive to AZD2014, but insensitive to rapamycin." (PMID 26219339, 2015). "Immunoblotting of 4 unrelated patient-derived primary NF2-deficient meningioma (MN) cell lines, as well as 3 NF2-null AC-CRISPR clones revealed increased SGK1 levels compared to control ACs." (PMID 26219339, 2015). "In particular, we demonstrate that independent activation of SGK1 and PAK1 may be partly responsible for the mTORC1 activation in NF2-deficient meningioma cells (model)." (PMID 26219339, 2015). "Interestingly, we observe increased SGK1 transcription and protein expression in NF2-CRISPR ACs and in primary NF2-negative meningioma lines." (PMID 26219339, 2015). "PAK1 inhibition also leads to attenuated mTORC1 but not mTORC2 signaling, suggesting that mTORC2/SGK1 and Rac1/PAK1 pathways are independently responsible for mTORC1 activation in NF2-deficient meningiomas." (PMID 26219339, 2015).
myocardial ischemia (3 papers, 2013 to 2023). A disorder of cardiac function caused by insufficient blood flow to the muscle tissue of the heart. "This research aimed to investigate the effect of coadministration of gallic acid and the GSK650394 (as SGK1 gene inhibitor) on the ischemic complications of a rat model of cardiac ischemia/reperfusion (I/R) injury." (PMID 36865044, 2023). "Specifically, the expression level of Col3a was significantly increased after myocardial ischemia and was further upregulated in SGK1-/- mice." (PMID 24265802, 2013). "In this study, we sought to define the SGK1 downstream signalling pathways in the adult heart and to elucidate their role in cardiac neo-angiogenesis and wound healing after myocardial ischemia." (PMID 24265802, 2013). "Furthermore, the decrease in microvessel density around the scar area in SGK1-/- hearts clearly demonstrates a beneficial role for SGK1 in neo-angiogenesis and wound healing after myocardial ischemia." (PMID 24265802, 2013). "In myocardial ischemia, lack of SGK1 blunts the phosphorylation of SGK1 target protein NDRG1 and compromises the up-regulation of transcription factor NF-κB and its target protein, VEGF-A (vascular endothelial growth factor A)." (PMID 31225494, 2018).
neuroblastoma (3 papers, 2013 to 2021). Neuroblastoma (NB) is the most common solid, extracranial childhood tumor. "To this aim, we generated a mouse neuroblastoma N2a cell line with genetic inactivation of all endogenous Sgk1 isoforms, in which we performed experiments using the proximity ligation assay (PLA)." (PMID 34899186, 2021). "This study showed a number of Akt-inhibitor-resistant lines displaying markedly elevated SGK1 that also exhibited significant phosphorylation of the SGK1 substrate NDRG1 [neuroblastoma-derived Myc (N-Myc) downstream-regulated gene 1]." (PMID 24782981, 2014). "This revealed a number of Akt-inhibitor-resistant lines displaying markedly elevated SGK1 that also exhibited significant phosphorylation of the SGK1 substrate NDRG1 [N-Myc (neuroblastoma-derived Myc) downstream-regulated gene 1]." (PMID 23581296, 2013).
preeclampsia (3 papers, 2024 to 2025). Preeclampsia is a hypertensive disorder of pregnancy that is characterized by new-onset hypertension with proteinuria presenting after 20 weeks of gestation, and depending on mild or severe forms may initially present with severe headache, visual disturbances, and hyperreflexia. "Higher predicted expression of 12 genes (including ATG16L1, BECN1, EP300, SGK1) was associated with increased odds of preeclampsia, while higher predicted expression of 17 genes was associated with decreased risk." (PMID 41220585, 2025). "Renal gene expression of Hsd11b2, Sgk1, Scnn1a, Nox4, and Fn1 was not different between mice who had a normal pregnancy and mice who had a preeclampsia-like pregnancy at 5 or 10 weeks postpartum (respectively)." (PMID 40425613, 2025).
steatosis (3 papers, 2018 to 2023). Increased lipid within the cytoplasm of cells. "Moreover, K48‐linked poly‐ubiquitination levels of SGK1 were significantly decreased in steatosis‐induced IMR‐90 and A549 cells, while K63‐linked poly‐ubiquitination levels were not affected." (PMID 37345264, 2023). "Here, we found that overexpression of p16 resulted in increased expression of SGK1 in steatosis‐induced IMR‐90 cells." (PMID 37345264, 2023). "In the steatosis network, the main identified triggers were an increase in the stress response, as indicated by an increase in SGK1 level." (PMID 35865277, 2022). "In addition, our co‐IP data showed that SGK1 ubiquitination levels were significantly reduced 6 h after the induction of steatosis in IMR‐90 and A549 cells." (PMID 37345264, 2023). "Next, we sought to determine whether inhibition of SGK1 could inhibit p16‐mediated activation of the integrin‐inflammasome pathway during non‐inflammatory steatosis in vitro." (PMID 37345264, 2023).
Stroke (3 papers, 2018 to 2024). Sudden impairment of blood flow to a part of the brain due to occlusion or rupture of an artery to the brain. "This suggests that SGK1 may also be associated with a high rate of stroke in aging." (PMID 36865044, 2023). "Elsewhere, the protective effect exerted by a-phenyl-n-tert-butyl nitrone in stroke is mediated by rapid induction of SGK1 expression." (PMID 39737082, 2024). "Since SGK1 regulates the activity of transporters and ion channels and affects blood pressure (BP), it is very likely that SGK1 influences stroke outcome." (PMID 36865044, 2023). "Therefore, the ultimate effect of SGK1 on stroke requires further exploration of the deeper mechanisms." (PMID 39737082, 2024).
ulcerative colitis (3 papers, 2022 to 2024). An inflammatory bowel disease involving the mucosal surface of the large intestine and rectum. "Our findings indicated that DPP10, MST1L, DPP10‐AS1, CEP55, ACSL1, MGP, OLFM4, and SGK1 may act as diagnostic biomarkers for ulcerative colitis and that differential immune infiltration cells may help to illustrate the progression of ulcerative colitis." (PMID 34939750, 2022). "To further validate the expression of these candidate biomarkers in ulcerative colitis, we determined mRNA levels of SGK1, CEP55, ACSL1, OLFM4, and DPP10 in LPS‐stimulated Raw264.7 cells by qPCR in in vitro bioassays." (PMID 34939750, 2022). "To further validate these biomarkers' expression in ulcerative colitis, we determined mRNA levels of SGK1, CEP55, ACSL1, OLFM4, and DPP10 in lipopolysaccharides (LPS)‐stimulated Raw264.7 cells by quantitative reverse transcription‐polymerase chain reaction." (PMID 34939750, 2022). "Compared with the normal group, the expression of SGK1, CEP55, ACSL1, OLFM4, and MGP was markedly increased in the DSS‐induced ulcerative colitis group." (PMID 34939750, 2022).
adrenocortical adenoma (2 papers, 2015 to 2020). "Using high-resolution single nucleotide polymorphism microarrays (Affymetrix SNP 6.0) to detect copy number alterations (CNAs) related to early adrenocortical adenomas, SGK1 was identified to be involved in tumorigenesis of adrenocortical adenoma." (PMID 33542904, 2020).
atopic dermatitis (2 papers, 2025 to 2026). "In addition, these authors found that Sgk1 inhibition enhances macrophage polarization to an inflammatory (M1) phenotype and that Sgk1 is downregulated in macrophages in skin samples from patients with psoriasis and atopic dermatitis." (PMID 40943265, 2025).
bladder cancer (2 papers, 2014 to 2022). "Tumor suppressor and other cancer-associated genes were also identified, including TNFAIP3, SGK1, and PSCA, which have been implicated in MM or bladder cancer." (PMID 24466111, 2014).
developmental delay (2 papers, 2013 to 2025). "sgk-1(ft15) emerged from a genetic screen for suppressors of the developmental delay phenotype of animals harboring a loss-of-function mutation in lpo-6/rict-1, which encodes the C. elegans ortholog of the TOR complex 2 component Rictor." (PMID 23786484, 2013). "We also tested a sgk-1 (gf) allele, that suppresses some rict-1 phenotypes entirely (such as those associated with learning, fat storage, body size, and developmental delay." (PMID 39829881, 2025). "The sgk-1 gain of function allele (ft15) suppresses some rict-1 mutant phenotypes (such as associated learning, fat storage, body size, and developmental delay)." (PMID 39829881, 2025).